SIRT1 (sirtuin 1)
Diseases named in the same sentence as SIRT1 in open-access papers (continued):
Sharing a sentence is not in itself a finding about the gene and the disease.
colorectal cancer (continued). "On the other hand, miR-34a acts as an immunosuppressive miRNA in colorectal cancer via regulation of SIRT1/NF-κB/B7-H3/TNF-α axis." (PMID 37441551, 2023). "Specifically, we demonstrate that EA meliorates inflammation and promotes autophagy in colorectal cancer via SIRT1/miR-215/Atg14 Axis." (PMID 38006398, 2023). "To further confirm that KIAA1429 regulated the growth of colorectal cancer cell via SIRT1, we knockdown KIAA1429 and then overexpressed SIRT1." (PMID 35217651, 2022). "The function of promoting the proliferation and metastasis of SIRT1 was also observed in pancreatic cancer, colorectal cancer, lung cancer, and other cancers." (PMID 35350833, 2022). "Treatment of colorectal cancer cells with RSV increased SIRT1 activation, decreased proliferation, invasion/metastasis, and increased mesenchymal to epithelial transition (MET)." (PMID 36558430, 2022). "Recent studies have indicated that aberrant overexpression of SIRT1 is correlated with metastasis and poor prognosis in several types of malignancy, including colorectal cancer." (PMID 34826187, 2022). "The inhibitor of ACOX1 is SIRT1, which has been proved to prevent oxidative damage and is downregulated in liver cancerr, suppresses colorectal cancer metastasis by transcriptional repression of miR-15b-5p44." (PMID 33767290, 2021). "It has been largely demonstrated that SIRT1 is a major target of resveratrol, and several studies demonstrated that SIRT1 upregulation is required for resveratrol-mediated chemopreventive effects in colorectal cancer cells." (PMID 33669559, 2021). "It is reported that natural compounds such as calebin A and resveratrol can induce colon cancer cell apoptosis and prevent colorectal cancer metastasis by targeting SIRT1 and inhibiting NF-κB signaling." (PMID 34765011, 2021). "SIRT1 represses the metastasis of colorectal cancer through transcriptional suppression of miR-15b-5p." (PMID 33526036, 2021). "It was found that the SIRT1 level was higher in patients with colorectal cancer than in healthy subjects (737.3 pg/mL vs. 443.80 pg/mL; p = 0.001)." (PMID 34942940, 2021). "Increased levels of c-Myc in the human colorectal cancer cells positively correlate with high SIRT1 protein expression; furthermore, conditional activation of c-Myc increases levels of SIRT1 protein, NAD+, and NAMPT mRNA in several cell types." (PMID 31689236, 2019). "On the other hand, the activation of SIRT1 and AMPK has been associated with the induction of senescence in colorectal carcinoma cells." (PMID 31781355, 2019). "We therefore demonstrated that miR-29b reverses oxaliplatin-resistance in colorectal cancer by targeting SIRT1/ROS/JNK pathway." (PMID 29552311, 2018). "Overexpression of SIRT-1 was found to promote proliferation and metastasis in osteosarcoma, pancreatic cancer, lung cancer and colorectal cancer." (PMID 29552311, 2018). "In summary, we demonstrated that TCO induced autophagy via the upregulation of SIRT1 in colorectal cancer cells." (PMID 28881770, 2017). "Previous experimental studies using in vitro and in vivo models of human colorectal cancer have shown that SIRT1 exhibited pleiotropic effects, i. e., tumor-suppressive and growth-promoting effects, depending on cellular context." (PMID 28977971, 2017). "The levels of high SIRT1 expression in colorectal cancer ranged from 37.0% to 67.0%, and ranged from 27.9% to 82.2% in non-colorectal gastrointestinal cancers." (PMID 28977971, 2017).
colorectal cancer (continued). "In colorectal cancer, the overall evidence from published studies has been insufficient to establish a correlation between SIRT1 expression and OS." (PMID 28977971, 2017). "The histone deacetylase Sirt1 is a major subcellular target of resveratrol and is a major target for resveratrol-mediated suppression of colorectal cancer cell growth and metastasis." (PMID 28953264, 2017). "Further studies with large sample sizes and stratified analyses according to clinicopathological characteristics, as well as other colorectal cancer-related molecular biomarkers, are needed to evaluate the prognostic role of SIRT1 more precisely." (PMID 28977971, 2017). "Collectively, these results indicated that TCO-induced autophagy in colorectal cancer cells was mediated by the upregulation of SIRT1." (PMID 28881770, 2017). "SIRT1 has been generally over-expressed in gastrointestinal cancers, including liver, pancreatic, and colorectal cancers, suggesting a putative role for SIRT1 consistent with tumor promotion." (PMID 28977971, 2017). "To further explore the mechanisms responsible for SIRT1 dysregulation in the metastatic process of colorectal cancer, we employed array analysis of human tumor metastatic genes after silencing of SIRT1 in CRC cells." (PMID 27145368, 2016). "SIRT1 is upregulated in patients with prostate, breast, pancreatic, and colorectal cancers and plays a critical role in tumor initiation, progression, and drug resistance." (PMID 26363315, 2015). "Previous studies on the role of Sirt1 in colorectal cancer have used mice, in which the exon 4 of Sirt1 was deleted or in which Sirt1 was overexpressed in the intestine." (PMID 25013930, 2014). "In order to determine an involvement of c-MYC and SIRT1 in the tumorigenesis of the serrated route to colorectal cancer, we analyzed their expression in a well characterized collection of serrated polyps and carcinomas." (PMID 23045412, 2012). "Once we had made the vectors, we were able to obtain SirT1 KO cells from the colorectal cancer cell line HCT116 and HDAC2 KO cells from the colorectal cancer cell line DLD1." (PMID 23046873, 2012). "Taken together, we provide evidence that c-MYC and SIRT1 are crucially involved in the alternative, serrated pathway to colorectal cancer." (PMID 23045412, 2012). "The increasing expressions with higher grades of malignancy suggest crucial functions for c-MYC and SIRT1 in the progression of serrated lesions to colorectal cancer." (PMID 23045412, 2012). "In colorectal cancer of the classical route SIRT1 is overexpressed, which correlates with high c-MYC expression." (PMID 23045412, 2012). "Circ-SIRT1 promotes colorectal cancer cell proliferation by recruiting and binding eIF4A3." (PMID 41002382, 2025). "Moreover, NSD2 directly methylates active regulator of SIRT1 (AROS) at K27 to facilitate its interaction with SIRT1, resulting in SIRT1 activation and enhanced fatty acid oxidation in colorectal cancer." (PMID 41301842, 2025). "Furthermore, SIRT1 exhibits both oncogenic and oncosuppressor functions in colorectal carcinoma (CRC), prostate, and breast cancer." (PMID 39215785, 2025). "Furthermore, SMURF2 interacts with and degrades sirtuin 1 (SIRT1), with its depletion leading to increased SIRT1 levels, promoting colorectal cancer formation and growth." (PMID 39697237, 2024). "Sirt1 has also been reported to be an autophagy-related gene in colorectal cancer." (PMID 38214831, 2024). "As a result, Sirt1 may be regarded as a prospective therapeutic target for colorectal cancer as well as a possible prognostic marker." (PMID 38427808, 2024). "For example, earlier research reported that SIRT1 mutations were more common in colorectal cancer and non-small cell lung cancer." (PMID 39845948, 2024).
colorectal cancer (continued). "Similarly in colorectal cancer research, SIRT1 can reduce the transactivation of miR-15b-5p by AP-1 through the deacetylation of activating protein (AP-1)." (PMID 39409719, 2024). "In colorectal cancer, SIRT1 typically stimulates autophagy to inhibit apoptosis." (PMID 39403142, 2024). "Furthermore, SIRT1 has been found to be highly expressed in stem-like colorectal cancer cells, its expression co-localized with CD133, a widely used marker of colorectal CSCs." (PMID 38397988, 2024). "Using azoxymethane/dextran sulfate sodium- (AOM/DSS-) induced colorectal cancer model in mice, we explored whether EA treatment can inhibit inflammation and promote autophagy via the SIRT1/miR-215/Atg14 axis." (PMID 38006398, 2023). "Notably, T2102 deterred the proliferation of the DLD-1 human colorectal cancer cell line by deactivating β-catenin through SIRT1-facilitated deacetylation." (PMID 37962461, 2023). "In a quest to spotlight foods and constituents boasting anti-aging potential, a trailblazing system was established, targeting substances that could ignite the SIRT1 promoter in human colorectal cancer cells." (PMID 37962461, 2023). "SIRT1 plays a dual role in cancer promotion and suppression, depending on tissue contexts and the temporal and spatial distribution of SIRT1 upstream and downstream factors, whereas SIRT1 is an oncoprotein that promotes the stemness of colorectal cancer cells, as well as liver cancer stem cells." (PMID 37490168, 2023). "Both in vivo and in vitro studies showed that SIRT1 overexpression could promote the migration and invasion of colorectal cancer cells while reducing SIRT1 expression inhibited the migration and invasion of the cells." (PMID 37293593, 2023). "Similarly, autophagy-induced by SIRT1 is also involved in 5-FU (5-fluorouracil) resistance in colorectal cancers." (PMID 31861179, 2019). "Moreover, miR-22 suppressed EMT process and cancer distant metastasis by directly targeting TIAM1 (T-cell lymphoma invasion and metastasis 1) and SIRT1 in colorectal cancer and renal cell carcinoma, respectively." (PMID 29434190, 2018). "For this reason, we next addressed whether SIRT1 is involved in TCO-induced autophagy in colorectal cancer cells." (PMID 28881770, 2017). "TCO treatment promoted SIRT1 expression in colorectal cancer cells and increased LC3-II conversion." (PMID 28881770, 2017). "Nevertheless, it is noteworthy that SIRT1 was specifically over-expressed in colorectal serrated lesions with KRAS or BRAF mutations, possibly contributing to their malignant transformation into colorectal cancer." (PMID 28977971, 2017). "Similar to our observations, SIRT1-deficiency reduced polyp area and size in the APC+/min model of colorectal cancer and reduced the number and the size of tumors in a colitis-induced colorectal cancer model." (PMID 27494892, 2016). "Interestingly, miR-34a can negatively regulate 5-FU resistance in human colorectal cancer DLD-1 cells by targeting the SIRT1 and E2F3 genes." (PMID 25585539, 2015). "In colorectal cancer, c-Myc increased both SIRT1 protein level and deacetylase activity of SIRT1." (PMID 23024800, 2012). "Furthermore, with higher grades of malignancy and invasiveness the expression of c-MYC and SIRT1 consistently increased, implicating a so far unrecognized role of c-MYC and SIRT1 in the tumorigenesis of the serrated route to colorectal cancer." (PMID 23045412, 2012). "However, the direct effect of vitamin D on SIRT1 activity and protein expression in colorectal cancer remains unclear." (PMID 40284214, 2025).
colorectal cancer (continued). "In addition, Resveratrol inhibits colorectal cancer progression by activating SIRT1, inhibiting the expression of the transcription factor FOXQ1, and controlling the regulatory promoter region of the 3′-UTR of the key autophagy molecule ATG16L, which triggers autophagy-related apoptosis." (PMID 39479446, 2024). "Moreover, SIRT1 overexpression is more frequently observed in advanced-stage colorectal cancers." (PMID 35163511, 2022). "Therefore, our study appears to support a tumor promoter role for SIRT1 in colorectal cancer." (PMID 30451820, 2018). "A further subgroup analysis of Asian patients according to cancer type showed that there was a significant association between SIRT1 and worse OS in non-colorectal gastrointestinal cancer (sHR 1.86, 95% CI = 1.50-2.30), but not in colorectal cancer (sHR 1.30, 95% CI =0.78-2.18)." (PMID 28977971, 2017). "Moreover, we could demonstrate previously that resveratrol-induced Sirt1 up-regulation is required for the resveratrol-mediated chemopreventive effects in colorectal cancer cells." (PMID 28953264, 2017). "However, the mechanisms involved in such different functions of SIRT1 in colorectal cancer remain unclear." (PMID 28977971, 2017). "In colorectal cancer, PUS7 facilitates cancer cell migration through the HSP90/PUS7/LASP1 pathway, enhances proliferation via SIRT1 activating the Wnt/β-catenin pathway, and stimulates proliferation and invasion through the PI3K/AKT/mTOR signaling pathway." (PMID 41554761, 2026). "The results of our meta-analysis are in agreement with the findings of SIRT1 being upregulated more frequently in T3 + T4, lymph node metastases, and TNM stage of colorectal cancer patients." (PMID 39403142, 2024). "Research indicates that SIRT1 can bind to the miR-20b-3p promoter, mediating the miR-20b-3p/DEPDC1 axis and enhancing L-OHP resistance in colorectal cancer." (PMID 39409719, 2024). "Recent studies have shown that SMURF2 interacts with SIRT1 to mediate the degradation of SIRT1, while deletion of SMURF2 expression leads to upregulation of SIRT1, inducing tumor initiation and the invasive metastasis of colorectal cancer in vivo and in vitro." (PMID 37828084, 2023). "NCAPD2 is similarly upregulated in colorectal cancer and NCAPD2 inhibits autophagy and promotes CRC cell proliferation and migration through the Ca2+/CAMKK/AMPK/mTORC1 pathway and PARP-1/SIRT1 axis." (PMID 37498296, 2023). "NCAPD2 plays a role in colorectal cancer through Ca2+/CAMKK/AMPK/mTORC1 pathway and PARP-1/SIRT1 axis and can be used as a potential therapeutic target." (PMID 37192046, 2023). "The Wnt/β-catenin signaling pathways is also activated in colorectal cancer by the lncRNA NEAT1 (nuclear-enriched abundant transcript 1), which modulates the miR-34a/SIRT1 axis." (PMID 36012617, 2022). "We successfully depleted the SIRT1 gene in human colorectal carcinoma COLO 320DM cells using CRISPR/Cas9 and examined SIRT1 protein expression in isolated clonal cells by Western blotting." (PMID 33539925, 2021). "In colorectal cancer (CRC), both confirmed tumor-suppressive and tumor-promoting functions of SIRT1 have been reported." (PMID 30093977, 2018). "As expected, inhibition of SIRT1 activity by its inhibitor, EX-527, attenuated TCO-induced autophagy, as evidenced by decreased LC3-II conversion and LC3 puncta in colorectal cancer cells." (PMID 28881770, 2017).
colorectal cancer (continued). "Authors have demonstrated that silencing of Sirt1 significantly abrogated the resistance to 5-FU in the 5-FU-resistant cells, suggesting that targeting the Sirt1 gene could negatively regulate, at least in part, the resistance to 5-FU in human colorectal cancer." (PMID 24527460, 2014). "One such example is the role in the intestine where both Sirt1 inactivation and Sirt1 overexpression in the APC Min model of colorectal cancer led to reduced tumor development." (PMID 25594010, 2014). "Using this method, we constructed SirT1 and HDAC2 KO vectors, which were used to establish SirT1 KO cells from the colorectal cancer cell line (HCT116) and HDAC2 KO cells from the colorectal cancer cell line (DLD1)." (PMID 23046873, 2012). "HDAC1, HDAC5, HDAC7A, SIRT1, and SUV39H1 expression profiles were distinctive for colorectal cancers and normal colorectal mucosa." (PMID 16638127, 2006). "Similarly, in colorectal cancer, MSI-H tumors are characterized by SIRT5/LDHB-dependent metabolic control, while MSS tumors show stronger regulation by chromatin modifiers such as SIRT1 and SIRT7." (PMID 41213956, 2025). "SIRT1 expression levels were significantly correlated with clinicopathological features including tumor differentiation degree, depth of invasion, TNM stage, distant metastasis (in colorectal cancer), and lymph node metastasis (in RC) (p < 0.05)." (PMID 41020376, 2025). "Additionally, in colorectal cancer, PUS7 exerts oncogenic effects by interacting with Sirtuin 1 (SIRT1) and activating the Wnt/β-catenin signaling pathway." (PMID 40940790, 2025). "SIRT1 expression was not connected with these clinicopathological aspects, but rather a poor predictive biomarker of colorectal cancer patients." (PMID 39403142, 2024). "SIRT1 inhibition increases the acetylation of mitochondrial calcium uniporter (MCU), leading to mitochondrial Ca2+ overload and depolarization, and ultimately to apoptosis in colorectal cancer (CRC) cells." (PMID 39479446, 2024). "It has been reported that the levels of P‐SIRT1Ser47 as well as SIRT1 are higher in colorectal cancer tissues than in adjacent normal tissues." (PMID 34826187, 2022). "Unlike SIRT2 and SIRT4, in the colorectal cancer, SIRT1 was reported to participate in the tumorigenesis, and its expression is positively correlated with the cancer progression in clinic." (PMID 35217651, 2022). "In two studies using an in vitro colorectal cancer model, catalpol was found to promote apoptosis and autophagy in colorectal cancer cells, either via the PI3K-Akt signaling pathway or by directly inhibiting sirtuin 1 (SIRT1) expression." (PMID 34578851, 2021). "Jung and colleagues observed that aspirin induced senescence in two colorectal carcinoma cell lines, but not in normal colonic cells, through the increased expression and deacetylase activity of SIRT1 and the increased activation of AMPK." (PMID 31781355, 2019). "In this study, our results demonstrated that TCO treatment increased SIRT1 expression in colorectal cancer cells, and inhibition of SIRT1 activity by EX-527 attenuated TCO-induced autophagy, suggesting that SIRT1 plays a critical role in TCO-induced autophagy in colorectal cancer cells." (PMID 28881770, 2017). "In conclusion, high SIRT1 expression is a potential marker for poor survival in non-colorectal gastrointestinal cancer, but not in colorectal cancer." (PMID 28977971, 2017). "Further research is needed to investigate the prognostic role of SIRT1 in colorectal cancer and other gastrointestinal cancer in non-Asian areas." (PMID 28977971, 2017). "Our results supported the previous studies, including a recent meta-analysis, showing that SIRT1 is not an independent prognostic factor for survival in colorectal cancer." (PMID 28977971, 2017). "Moreover, Menssen and collaborators found a positive feedback loop between SIRT1 and MYC activation in colorectal cancer." (PMID 29383100, 2017).